TNF (tumor necrosis factor)
Diseases named in the same sentence as TNF in open-access papers (continued):
Sharing a sentence is not in itself a finding about the gene and the disease.
endothelial dysfunction (continued). "Particularly, TNF-α seems to be connected to endothelial dysfunction and the overexpression of adhesion molecules, making it easier for immune cells to be attracted to the vascular wall, which is a critical stage in plaque development." (PMID 37893519, 2023). "The endothelial expression of LINC00607 was increased by hypoxia, EndMT, and endothelial dysfunction as induced by TNFα and high glucose." (PMID 36700983, 2023). "Subsequently, three boluses of 10% fresh aqueous CSE and/or 5 ng/mL TNFα were injected into the flow system at 16 h intervals to simulate the sustained endothelial dysfunction experienced by smokers." (PMID 36804807, 2023). "A study in animals with induced diabetes has demonstrated that TNF-α and IL-6 exacerbated oxidative stress and inhibited the eNOS activity, thereby contributing to an endothelial dysfunction." (PMID 36674022, 2023). "One of the main targets of TNF is the endothelium, where it initiates a cascade of events leading to endothelial dysfunction." (PMID 37834170, 2023). "ASMase mediated TNF-α-induced endothelial dysfunction through inhibiting eNOS phosphorylation and activating of MAPK signaling, which were restored by its inhibitor, amitriptyline." (PMID 36732747, 2023). "Here, we demonstrate that endothelial dysfunction induced by TNF-α increased endothelial oxidative stress and induced apoptosis via mitochondrial cytochrome c release and caspase activation over 24 h." (PMID 36978982, 2023). "In humans, evidence points towards TNF-α playing an important role in stimulating endothelial dysfunction." (PMID 37745103, 2023). "In particular, the endothelial dysfunction disrupts the regulatory balance by decreasing nitric oxide and promoting an increase of interleukin-6 (IL-6), tumor necrosis factor (TNF-α), and blood levels of CRP." (PMID 37568542, 2023). "Meanwhile, in vitro knockdown of FGFR1 by siRNA activated ROCK2, leading to endothelial dysfunction with increased adhesive properties and permeability in TNFα-treated HUVECs." (PMID 36969192, 2023). "They act in a mechanism similar to that of TNF-α by inhibiting NO production and increasing the release of endothelin-1, thus leading to endothelial dysfunction and resulting in arterial stiffness." (PMID 37859889, 2023). "Neutralising TNF-α therapies in inflammatory arthritis successfully suppressed endothelial dysfunction, apoptosis and mitochondrial damage in patients with cardiovascular comorbidities." (PMID 36978982, 2023). "Endothelial dysfunction and local inflammation lead to activation of the endothelium via cytokines such as tumor necrosis factor or interleukin 1 beta." (PMID 37086290, 2023). "A multicenter prospective longitudinal study found a significant improvement in arterial pulse wave velocity in IBD patients after receiving long-term anti-TNF therapy, indicating that decreased inflammation improves endothelial dysfunction." (PMID 37638002, 2023). "In fact, n-3 polyunsaturated fatty acids can decrease the production of pro-inflammatory mediators, such as TNF-α, and alter the signalling pathways that regulate gene expression, such as NF-kB activity, helping to counteract endothelial dysfunction." (PMID 37107183, 2023). "T cells and macrophages, as producers of the pro-inflammatory cytokines TNF-α and interleukins (ILs), are central factors in endothelial dysfunction and vascular remodeling." (PMID 36140374, 2022). "ET1 and VCAM are markers of endothelial dysfunction, expression of both can be induced by the pro-inflammatory cytokine TNFα." (PMID 36417467, 2022). "TNF-α, one of the most important pro-inflammatory cytokines in RA, is also produced by foam cells and contributes to endothelial dysfunction." (PMID 35628831, 2022). "TNF-α activates the transcription of NF-kB, regulating the expression of genes involved in inflammation, oxidative stress, and endothelial dysfunction." (PMID 35163364, 2022).
endothelial dysfunction (continued). "There is a growing body of evidence suggesting that TNF-α-mediated inflammation plays a crucial role in the development of endothelial dysfunction." (PMID 35206342, 2022). "In turn, TNF-α can decrease the expression of endothelial nitric oxide (NO) synthase, resulting in reduction of the bioavailability of NO and leading to endothelial dysfunction, and consequently, elevation of BP." (PMID 36247461, 2022). "Dihydromyricetin attenuates TNF-α-induced endothelial dysfunction via miR-21-mediated DDAH1/ADMA/NO pathway, which further supports our findings." (PMID 36561848, 2022). "In obese rats, nicotine administration caused a further rise in oxidative stress, inflammation, and endothelial dysfunction markers, probably by a pathway involving TNF-α." (PMID 36262466, 2022). "Plasma TNF-α plays a crucial role in both inflammation-mediated redox distress and endothelial dysfunction and regeneration, affecting NOS3 and VEFGA expression." (PMID 35203700, 2022). "In conclusion, a beneficial effect of anti-TNF-α therapy on cell-surface heparan sulfate proteoglycans (HSPGs)/HS turnover and endothelial dysfunction was observed in this study." (PMID 35887981, 2022). "Previous studies have shown that TNF-α and IL-6 have atherogenic properties concomitantly with increased hCys and lead to endothelial dysfunction by vascular calcification." (PMID 35684085, 2022). "Circulating levels of Orai1 were correlated with the inflammatory factor TNF-α and with the endothelial dysfunction marker asymmetric dimethylarginine." (PMID 36429103, 2022). "Specifically, treatment of endothelial cells with 60 °C OPW extracts inhibited TNFα-induced vascular inflammation and endothelial dysfunction in vitro, suggesting that OPW possess vasoprotective effects likely mediated by anti-inflammatory effects." (PMID 36139842, 2022). "Based on the crucial role of TNF-α in improving endothelial dysfunction, the effects of different agents that block the action of TNF-α have been evaluated in different cardiovascular disorders and inflammatory conditions." (PMID 35206342, 2022). "Inflammation is an important factor of endothelial dysfunction, and it has been demonstrated that TNF-α impairs the endothelium-dependent relaxation by affecting nitric oxide production and inducing reactive oxygen species." (PMID 35237624, 2022). "Lactobacillus coryniformis CECT5711, a probiotic isolated from goat cheese, inhibits LPS and TNF-α expression in obese mice and reverses endothelial dysfunction in mice by increasing NO bioavailability." (PMID 36193065, 2022). "The TNF-α-NFκB signaling axis is a highly potent pro-inflammatory pathway and mediates multiple aspects of endothelial dysfunction." (PMID 36794234, 2022). "Systematic inflammation and circulating cyto- and chemokines including C-reactive protein, IL-6, IL1β, and TNFα fuel CVD through endothelial dysfunction, altered vascular tone, enhanced plaque formation, and coagulation." (PMID 36564799, 2022). "We also observed a TNF-α blockade affect manifested by a rapid reduction in the levels of HS/H, as well as endothelial dysfunction markers, following administration of TNFαI." (PMID 35887981, 2022). "Among the mechanisms of action, many of which have been explained in previous sections, TNF inhibitors improve endothelial dysfunction, oxidative stress and modify the lipid profile." (PMID 36352850, 2022). "The cytokines tumor necrosis factor alpha, interleukin-1 beta, and interleukin-6 have particular effects on endothelial cells—leading to endothelial dysfunction, endothelial cell death, changes in tight junctions, and vascular hyperpermeability." (PMID 35682871, 2022). "TNF-alpha expression has been demonstrated on the surface of microparticles promoting apoptosis and autophagy and contributing to endothelial dysfunction." (PMID 36352850, 2022). "IL-6 and TNF-α are considered potent oxidative stress-inducing agents, thus leading to endothelial dysfunction." (PMID 36009796, 2022).
endothelial dysfunction (continued). "The present study investigated the effect of anti-tumor necrosis factor-α (anti-TNF-α) therapy in combination with methotrexate on plasma sGAG levels and serum markers of endothelial dysfunction." (PMID 35887981, 2022). "IL-6 also triggers hepatic synthesis of CRP, while TNF-α is more involved in the activation of inflammatory cytokine, endothelial dysfunction and induction of bone resorption." (PMID 33676486, 2021). "Silva and collaborators have previously demonstrated that a high sugar diet, in addition to inducing endothelial dysfunction, upregulates the TNFα and iNOS pathways, decreasing vascular contractility in the aortas of obese male animals." (PMID 34566644, 2021). "IPA downregulates matrix metalloproteinase-13 activity, which prevents cartilage destruction and increases eNOS activity and NO production, thereby inhibiting tumor necrosis factor alpha (TNF-α)-induced endothelial dysfunction." (PMID 33466670, 2021). "Astragaloside IV combined with ferulic acid can intervene NF-κB, TNF-α pathway and improve the endothelial dysfunction of diabetic vascular disease." (PMID 34593896, 2021). "Vitamin D improves endothelial dysfunction by reducing the oxidative stress of free oxygen radicals, TNF-alpha and interleukin-6 and suppressing the NF-κB pathway." (PMID 34475485, 2021). "The use of novel improved molecular cut-off MCO dialyzers shifted the TNF-α/sTNF-R1-ratio and inflammatory milieu in patient serum to ameliorate endothelial dysfunction." (PMID 34858433, 2021). "As a result, proinflammatory cytokines, for example IL-6 and TNF-alpha stimulate neutrophils (PMNs) and monocytes thereby inciting a hyperinflammatory response, vascular leakage, and endothelial dysfunction." (PMID 34457265, 2021). "TNF-α increasing ROS levels and decreasing nitric oxide production in blood vessels leads to endothelial dysfunction." (PMID 33628326, 2021). "Other factors leading to endothelial dysfunction include the pro-inflammatory cytokines TNF-α and IL-1." (PMID 33459124, 2021). "Other pro-inflammatory molecules are related to endothelial dysfunction, like IL-6, TNF-α, monocyte chemoattractant protein 1 (MCP-1), and the pro-oxidant enzyme NADPH oxidase, all of which predispose the vasculature to CVD." (PMID 33467601, 2021). "The increased PVR was accompanied by higher circulating levels of TNF-α and ET-1, further reflecting inflammation and endothelial dysfunction." (PMID 34510273, 2021). "Plasma levels of interleukin 6 (IL-6) and tumor necrosis factor alpha (TNFα) were analyzed as markers of inflammation, and soluble tumor necrosis factor-like inducer of apoptosis (sTWEAK) as an endothelial dysfunction marker." (PMID 34046003, 2021). "It has been well-known that TNF-α induces endothelial cell inflammatory injury, apoptosis and endothelial dysfunction." (PMID 33967800, 2021). "Counteracting TNFα-mediated effects has proven to ameliorate endothelial dysfunction and vascular conditions." (PMID 34502180, 2021). "Circulating cytokines, such as TNF-α and IL-6, are related to the degree of endothelial dysfunction in HF, which correlates with progressive deterioration in HF functional class." (PMID 33804661, 2021). "As a part of chronic inflammation, endothelial cells are continuously activated by inflammatory stimuli, including IL-6, TNF-α, and IL-1β, resulting in endothelial dysfunction and the progression of fibrosis." (PMID 34202668, 2021). "Among the biomarkers of endothelial dysfunction and inflammation, both serum sVCAM-1 and TNF-α were significantly decreased after the 4-week high dose strawberry phase when compared to baseline, control, and low dose strawberry phases." (PMID 34829601, 2021). "As a result, a cascade of pro-inflammatory markers including IL-1β, IL-6 and TNF-α were upregulated, eventually leading to endothelial dysfunction, as displayed by EDR impairment." (PMID 40477401, 2021).
endothelial dysfunction (continued). "Recently, studies have focused on inflammatory biomarkers and risk factors for endothelial dysfunction, such as C-reactive protein (CRP), and tumor necrosis factor-α (TNF-α) that are considered to be prognostic factors for the development of DR." (PMID 33790859, 2021). "The proinflammatory cytokines, such as tumor necrosis factor (TNF)‐α and interleukin (IL)‐6, lead to endothelial dysfunction and activation, primarily in patients with RA." (PMID 34075600, 2021). "Protective potential against endothelial dysfunction was evaluated using TNF-α-induced human umbilical vein endothelial cells (HUVECs)." (PMID 33803343, 2021). "Endothelial dysfunction leads to cytokine release, including Il-1, Il-6 and TNF-alpha, culminating in increased blood brain barrier permeability." (PMID 34457265, 2021). "Agomelatine also suppressed the expression of TNF-α, IL-8, and IL-12, which are proinflammatory cytokines that promote endothelial dysfunction and atherogenesis." (PMID 34292876, 2021). "In certain trials, the TNFa (tumour necrosis factor alpha) antibody therapy seems to improve the endothelial dysfunction and vascular stiffness and to downregulate the mucosal angiogenesis in this population." (PMID 34070768, 2021). "TNFα induced endothelial dysfunction also significantly increased mRNA levels of IL-6, NLRP3 and PTGS2." (PMID 34362171, 2021). "Evidence number of studies have shown associations between tumor necrosis factor-α (TNF-α), and arterial elasticity, arterial inflammation, and endothelial dysfunction." (PMID 34776005, 2021). "Many previous studies have shown that inhibition of TNF-α expression can effectively reduce endothelial dysfunction." (PMID 34681733, 2021). "The inflammatory phase that leads to endothelial dysfunction is initiated by TNF-α and subsequently amplified by IL-1, IL-6 and downstream mediators." (PMID 33868242, 2021). "Adipose tissue (morphometry), plasma adiponectin, TNF-α, resistin (multiplexing) and biochemical chemistry were analyzed; as well as endothelial dysfunction (Flow Mediated Dilation, FMD) and atherogenesis (Carotid Intima Media Thickness, CIMT)." (PMID 33469087, 2021). "RAGE alters cell signaling pathways and contributes to endothelial dysfunction via tumor necrosis factor-α (TNF-α)." (PMID 33928164, 2021). "Oxidative stress and pro-inflammatory cytokines, such as tumor necrosis factor-α (TNF-α) contribute to endothelial dysfunction and large artery stiffening in postmenopausal women." (PMID 35821995, 2021). "When TNFα was added to HUVECs to induce endothelial dysfunction, IL-1b expression was significantly increased from control levels and decreased with doses of bisoprolol and metoprolol, but not carvedilol." (PMID 34362171, 2021). "This means that adiponectin suppresses TNFα expression and TNFα blockage increases adiponectin expression in coronary arterioles and aorta, regulating endothelial dysfunction and suggesting a role of adiponectin in the prevention of vascular damage in T2DM." (PMID 33081064, 2020). "Increased circulating levels of endothelial biomarkers, such as sVCAM-1 and TNF-α, are suggestive of endothelial dysfunction, and there is also evidence of a prothrombotic state and of dysregulation of the nitric oxide pathway." (PMID 32784589, 2020). "In a previous study, mice maintained on a BDM-derived diet showed suppression of pro-inflammatory cytokine, TNF-α, concomitant with endothelial dysfunction." (PMID 32435651, 2020). "In turn, oxidative stress triggers intravascular inflammation and endothelial dysfunction via the release of factors such as tumor necrosis factor-α (TNFα), interleukin-6 (IL6), IL10, C-reactive protein, and other factors, such as Hemoglobin F." (PMID 32679789, 2020). "The injection of anti-TNF-α antibody 3 h prior to ischemia–reperfusion was also shown to reduce endothelial dysfunction by reducing the production of endothelial ROS." (PMID 33053859, 2020).
endothelial dysfunction (continued). "Recently, we have shown that genetic knockout of TNFα gene lowers blood pressure and vascular inflammation and protects against endothelial dysfunction and vascular injury in DOCA salt-sensitive hypertension." (PMID 32851077, 2020). "Studies have shown that inflammatory factors IL-6, IL-1β, IL-18, and TNF-α are positively correlated with cardiovascular events and are also involved in the occurrence of endothelial dysfunction." (PMID 33014270, 2020). "Regarding the inflammatory process and endothelial dysfunction, we also found an increase in proinflammatory cytokines, such as TNF-α and IL-6, which augment monocytes adhesion to endothelial cells." (PMID 32795274, 2020). "In diabetic patients, high-AGE diet causes a significant increase in serum inflammatory markers [CRP and tumor necrosis factor α (TNF-α)] and endothelial dysfunction marker VCAM-1, whereas a low-AGE diet leads to a suppression of all these markers." (PMID 33062134, 2020). "Proinflammatory cytokines play a pivotal role in endothelial dysfunction and IL-1β and TNFα belong to the ones that have attracted the most attention because of their crucial involvement in CVD." (PMID 32923484, 2020). "We have shown that DMY improves TNF‐α–induced endothelial dysfunction by decreasing miR‐21 expression." (PMID 32301289, 2020). "TNF-α is also known to increase ROS levels and decrease nitric oxide production in blood vessels, which can lead to endothelial dysfunction: an initial step in atherogenesis." (PMID 33053859, 2020). "Endothelial cells treated with TNF-α represent a widely-used model to investigate the effects of natural compounds to modulate endothelial dysfunction and inflammation." (PMID 32397678, 2020). "In this study, we focused on the protective effect of bazedoxifene against TNF-α-induced endothelial dysfunction." (PMID 33381228, 2020). "In particular, DHA has been shown to prevent tumor necrosis factor alpha-induced endothelial dysfunction." (PMID 32878052, 2020). "Several cytokines have been reported to induce endothelial dysfunction, including TNF-α, IL-6, and IL-1b42." (PMID 32958516, 2020). "It is possible that inflammation is the one that downregulates adropin through the fallout of pro inflammatory cytokines, most prominently TNF-α, which consequently leads to endothelial dysfunction." (PMID 32518265, 2020). "This inflammasome is responsible for elevated levels of TNF-α (tumor necrosis-factor-α), a cytokine which plays a crucial role in insulin insensitivity and endothelial dysfunction." (PMID 33317034, 2020). "Proinflammatory cytokines, such as TNF-α, augmented lipolysis with a resultant rise in free fatty acids, contributing to endothelial dysfunction via reducing endothelial NO production and increasing ROS." (PMID 30959892, 2019). "The administration of either cytotrophoblast conditioned media, or TNFα to HUVECs significantly increased endothelial dysfunction marker, VCAM-1 expression (p < 0.0001)." (PMID 30659233, 2019). "We also chose to include a second model of inflammatory-mediated endothelial dysfunction by treating HUVECs with tumour necrosis factor-α (TNFα)." (PMID 30659233, 2019). "To explore the roles of inflammation, endothelial dysfunction, and oxidative stress in normoalbuminuric renal insufficiency, we examined levels of plasma TNF-α, IL-6, ET-1, and 8-OHdG in 209 T2DM patients with normoalbuminuria." (PMID 31637265, 2019). "As an alternative solution to link genes and regulatory elements in the context of endothelial dysfunction, we generated genomic contact maps by Hi-C using untreated and TNFα-stimulated (4 h) teloHAEC." (PMID 31287004, 2019). "Evidence has indicated that TNF-α induces endothelial dysfunction by activating Rho GTPase and MLC kinase, leading to the phosphorylation of Ser 19 in MLCs; this leads to the assembly of stress fiber and actomyosin contractility." (PMID 31096970, 2019).